ALB (albumin)
Diseases named in the same sentence as ALB in open-access papers (continued):
Sharing a sentence is not in itself a finding about the gene and the disease.
Hypoalbuminemia (continued). "The lack of an observed association between serum albumin levels 3–6 months prior to dialysis initiation indicates that hypoalbuminemia may develop closer to the time of dialysis initiation, likely driven by acute events rather than long-term trends." (PMID 40316919, 2025). "However, a decline in albumin synthesis results in hypoalbuminemia." (PMID 40777143, 2025). "Additionally, liver dysfunction also impairs albumin synthesis, contributing to hypoalbuminemia." (PMID 40303541, 2025). "Symptomatic treatment may include dietary modification to reduce sodium and fluid intake, diuretics to relieve edema, intravenous albumin infusions to correct hypoalbuminemia, as well as immunosuppressive agents such as corticosteroids or calcineurin inhibitors." (PMID 40868160, 2025). "In addition, we observed that patients that received more than three lines of therapy and those with hypoalbuminemia at diagnosis of multiple myeloma had a worse outcome compared to patients with a normal value of albumin and those that received one or two lines of therapy." (PMID 39941726, 2025). "However, the role of intravenous (IV) albumin infusion in correcting hypoalbuminemia in calciphylaxis remains unclear." (PMID 40600068, 2025). "For example, NLR has been associated with increased cardiovascular risk and insulin resistance, while NPAR, which combines neutrophil counts with albumin levels, may indicate long-term inflammatory states and metabolic dysregulation, such as hypoalbuminemia often observed in chronic diseases." (PMID 40181962, 2025). "Notably, hypoalbuminemia, a common feature in cirrhosis, may compromise the reliability of conventional AG measurements, necessitating adjustments for albumin levels." (PMID 40938881, 2025). "Concerning the mechanism of hypoalbuminemia, it is hypothesized that patients with low albumin levels may have higher serum levels of free colistin because the medication is 50% protein bound and preferentially binds to albumin." (PMID 41301633, 2025). "However, forpatients with preoperative hypoalbuminemia, the use of albumin in priming may bebeneficial owing to evidence that perioperative hypoalbuminemia is independentlyassociated with poor prognosis in cardiac surgery patients." (PMID 40630457, 2025). "The combination may be considered in select cases, particularly those with severe hypoalbuminaemia (e.g., serum albumin < 20 g/L), refractory oedema unresponsive to escalating diuretics and no contraindications to fluid expansion (e.g., absence of pulmonary congestion or cardiac dysfunction)." (PMID 41281089, 2025). "Notably, individuals with hypoalbuminemia exhibited significantly lower mean Hemoglobin (123.84 ± 20.66 vs. 128.65 ± 21.49 g/L; p = 0.045) and Zinc (88.40 ± 22.12 vs. 97.01 ± 21.96; p = 0.006) levels compared to those with normal albumin." (PMID 41536828, 2025). "However, reductions in osmotic pressure, intravascular antioxidative reserve, and other protective effects justify the potential use of albumin supplementation to prevent worsening outcomes, even though hypoalbuminemia itself serves as a marker of pathological processes." (PMID 40005472, 2025). "Future research should focus on confirming these associations in large, well-designed prospective studies and on evaluating whether correcting hypoalbuminemia through albumin supplementation can improve renal or overall clinical outcomes in this patient population." (PMID 41523521, 2025). "Future studies could evaluate albumin-corrected AG to account for hypoalbuminemia in cholangitis." (PMID 40486199, 2025). "Furthermore, normal serum albumin levels have been repeatedly established in patients suffering from poor nutritional status and/or anorexia, which leads us to consider inflammation as a primary mechanism to hypoalbuminemia in oncologic disease." (PMID 40103850, 2025).
Hypoalbuminemia (continued). "Among these patients, those who were moderately or severely malnourished with hypoalbuminemia were more likely to experience increased chemotherapy-induced toxicity compared to well-nourished patients (31% vs. 22%; p = 0.02) and those with normal albumin levels (54% vs. 41%; p = 0.04)." (PMID 40227705, 2025). "Albumin is also a negative acute-phase protein, where a hypoalbuminemia typically reflects an inflammatory state that is caused by infection and certain diseases and could lead to a substantially higher mortality risk in centenarians." (PMID 41065185, 2025). "Likewise, it has been shown that the absence of FcRn in the liver leads to hypoalbuminemia since it causes albumin retention within hepatocytes and increases the excretion of bile albumin." (PMID 40821792, 2025). "Although no patients in our cohort exhibited severe hypoalbuminemia, those with neurological impairment and low albumin levels may be at increased risk of zinc deficiency." (PMID 41487727, 2025). "On the fourth day, as edema persisted without significant reduction, it was suspected that the edema might also be related to the liver dysfunction and hypoalbuminemia secondary to chronic hepatitis B. Human albumin was administered to increase colloid oncotic pressure and further reduce edema." (PMID 40922353, 2025). "Laboratory findings showed that the complication group had a higher incidence of hypoalbuminemia, concomitant positivity in blood and cerebrospinal fluid cultures, elevated creatinine and blood urea nitrogen levels, and significantly lower pH and albumin levels (P < 0.05)." (PMID 41322235, 2025). "It was suspected that the albumin association was the result of the group effect, considering the marked hypoalbuminemia that PLE can cause, although this suspicion could not be confirmed with the available data." (PMID 40123416, 2025). "Additionally, as KD is characterized by hypoalbuminemia due to albumin leakage outside the blood vessels and reduced hepatic synthesis in the face of the acute phase response, we also investigated the relationship between sSema7A and albumin." (PMID 38678170, 2024). "Although we adjusted the PSM for several factors involved in determining serum albumin levels, we could not exclude that some clinical conditions that are associated with hypoalbuminemia are associated with a higher risk of cardiovascular events per se." (PMID 38323429, 2024). "Furthermore, hypoalbuminemia has been identified as a risk factor for the early occurrence of PDAP, which is consistent with the present findings, wherein low blood ALB was identified as a risk factor of PDAP and an independent risk factor for intractable PDAP." (PMID 38658811, 2024). "Additionally, liver dysfunction during sepsis may decrease albumin synthesis, while increased microvascular permeability may drive albumin into extravascular compartments, contributing further to hypoalbuminemia." (PMID 39272772, 2024). "In addition, the pharmacokinetics of the drug under critical conditions may vary greatly due to several physiological factors, such as hypoalbuminemia, as posaconazole binds strongly and in a high percentage (> 98%) to proteins, especially to serum albumin." (PMID 38530518, 2024). "In terms of total proteins and albumin levels, our results displayed no variation between baseline and follow-up, even though the literature links hypoalbuminemia and hypoproteinemia with obesity and a higher risk of developing postoperative complications in cases of low albumin levels." (PMID 40729297, 2024). "Moreover, as a major plasma protein and drug-binding agent, albumin critically influences drug distribution and metabolism; thus, hypoalbuminemia may alter hemorheological properties and therapeutic efficacy." (PMID 39474370, 2024). "However, in the ICU, because of the seriouscondition of the patients, many patients have hypoalbuminemia, and AG may appearpseudo-normal due to the charge of albumin." (PMID 39076311, 2024).
Hypoalbuminemia (continued). "However, the AUC value of the NPAR was lower than that of ALB in our study, indicating that hypoalbuminaemia may have a greater impact on mortality in peritoneal dialysis than chronic inflammation." (PMID 38178381, 2024). "However, our results suggest that, among the many variables that can be examined for assessing inflammation, hypoalbuminemia and lymphocytopenia (albumin and lymphocyte counts used to calculate PNI) are crucial variables for predicting septic AKI in the under 75 group." (PMID 38378647, 2024). "Moreover, albumin is a protein particularly consumed by an aggressive tumor, and hypoalbuminemia may impair the metabolism and the function of immune cells." (PMID 38541140, 2024). "Albumin levels were also significantly lower in non-survivors (2.8 g/dL) compared to survivors (3.3 g/dL) (p = 0.001), indicating that hypoalbuminemia may be linked to increased mortality." (PMID 39651035, 2024). "However, the contrary was observed in human studies, as albumin production was increased in chronically ill patients, leading to the hypothesis that a higher clearance rate leads to hypoalbuminemia in these patients." (PMID 39596952, 2024). "Therefore, we hypothesize that hypoalbuminemia may be an independent risk factor for CIA, as low serum albumin levels may increase the concentration of free cisplatin, thereby increasing the risk of CIA." (PMID 39723253, 2024). "Furthermore, in AECOPD patients with comorbidities, such as heart failure or chronic renal failure, serum albumin might be lost through urinary excretion, resulting in hypoalbuminemia." (PMID 39050134, 2024). "Indeed, it was estimated that 40%–90% of albumin prescriptions are unjustifiably given for correcting hypoalbuminemia per se, without considering the underlying disease process." (PMID 37432160, 2023). "While several different diseases cause hypoalbuminemia, they may not be the main reasons for the association between serum albumin and height loss." (PMID 37700384, 2023). "However, albumin infusions could significantly decrease mortality in hypoalbuminemia patients with SAP." (PMID 37277756, 2023). "Specific diseases that relate to hypoalbuminemia may not have the main explanation for the association between serum albumin and height loss." (PMID 37700384, 2023). "Additionally, infusing sufficient albumin within a week after admission may decrease mortality in hypoalbuminemia patients." (PMID 37277756, 2023). "Hypoalbuminemia (a serum albumin <3.0 g/dL in term neonates an <2.5 g/dL in preterm newborns) is a risk factor for bilirubin neurotoxicity, as low serum albumin levels may enhance the risk of bilirubin encephalopathy by lowering the bilirubin–albumin binding capacity." (PMID 37371159, 2023). "In addition, infusing a sufficient albumin dose within a week after admission may decrease mortality for hypoalbuminemia patients treated with albumin infusions." (PMID 37277756, 2023). "Low albumin levels are a strong predictor of atrial fibrillation following coronary artery bypass graft surgery in myocardial infarction, and prior research has shown that stroke patients with poor outcomes in the general population also had considerable hypoalbuminemia." (PMID 36739380, 2023). "However, whether hypoalbuminemia should be treated, or the appropriate timing and volume of albumin supplementation remain controversial." (PMID 37167307, 2023). "Furthermore, hypoalbuminemia was found to be an independent predictor of fatal sepsis in an intensive care unit, with a 75.2% increase in the mortality rate among patients with serum albumin <2.9 g/dL." (PMID 37065302, 2023). "In addition to the development of the disease itself, the condition of hypoalbuminemia could also be a consequence of the aging process, as albumin levels decrease with age." (PMID 37892441, 2023).
Hypoalbuminemia (continued). "In addition, in a clinical HCC cohort study, ALB levels were negatively correlated with tumour aggression parameters, implying that hypoalbuminemia may contribute to poor prognosis in HCC patients." (PMID 36720974, 2023). "Moreover, similar analysis results were also observed after excluding participants with possible hypoalbuminemia (n = 3480, including 600 serum albumin less than 35 g/L and 2880 missing serum albumin data) or excluding participants who died in the first two years (n = 953)." (PMID 37985990, 2023). "One possible example is that serum albumin might play a role in preventing autophagy; however, the level of autophagy in diabetic heart tissue is significantly increased, thereby amplifying the deleterious impact of hypoalbuminemia." (PMID 36966329, 2023). "Additional mechanisms accounting for this hypoalbuminemia might include systemic inflammation, as albumin is a negative acute-phase protein, and albumin renal loss, as proteinuria occurs in both dogs and humans envenomed by viperid snakes." (PMID 37888640, 2023). "However, this risk continues in patients whose albumin does not improve after the onset of PD or in patients who develop hypoalbuminemia." (PMID 36762995, 2023). "Furthermore, infusing a sufficient albumin dose could decrease mortality for hypoalbuminemia patients with albumin infusions." (PMID 37277756, 2023). "However, we could confidently conclude that PLE was responsible for hypoalbuminemia as the good response of serum albumin following steroid treatment." (PMID 37180328, 2023). "In addition, it inhibits the hepatic synthesis of the albumin and, together with other inflammatory cytokines, increases vascular endothelium permeability, favoring the leakage of the albumin into the extravascular space (hypoalbuminemia)." (PMID 37176761, 2023). "In our study, among the 39 patients who had hypoalbuminemia, four (6.67%) patients had preoperative serum albumin levels less than 2 g/dL, 22 (36.67%) patients had preoperative serum albumin levels of 2-3 g/dL, and 13 (21.67%) patients had serum albumin level of 3-3.4 g/dL." (PMID 36589182, 2022). "In addition, the altered ratio between free testosterone and albumin‐bound testosterone could explain ED in patients with hypoalbuminemia." (PMID 35817418, 2022). "However, hypoalbuminemia was not an independent predictor for mortality or postoperative complications, but low albumin values were associated with a higher CCI and ASA grade than in patients with a BMI below 20 kg/m2." (PMID 36363567, 2022). "On the other hand, some studies have revealed that therapy with intravenous albumin may improve organ function, respiratory status, and ventilation-perfusion matching in critically ill patients with hypoalbuminemia or patients with acute respiratory distress syndrome." (PMID 36077496, 2022). "Additionally, it should be noted that low levels of serum albumin, one of the major plasma proteins, are very common in critically ill patients, and this hypoalbuminemia is reported to affect the PK (mainly distribution Vd and clearance CL) of highly protein-bound antibacterial agents." (PMID 35884156, 2022). "In these aspects, exogenous albumin has been empirically used to replace intraoperative volume loss while minimizing edema in patients undergoing PD, even in patients without significant hypoalbuminemia." (PMID 35160076, 2022). "Moreover, the GO impact on Albumin production could determine hypoalbuminemia with a consequent alteration of drug distribution and pharmacokinetics." (PMID 35662849, 2022). "In addition, we did not exclude other causes of hypoalbuminemia, and we recorded only the baseline albumin values on the day of hospitalization for all patients." (PMID 36197158, 2022). "In addition, we found that serum albumin level or the presence of hypoalbuminemia was not a risk factor affecting long-term outcome in patients with massive proteinuria." (PMID 35488221, 2022).
Hypoalbuminemia (continued). "In addition, using univariate logistic regression, we found that serum albumin level or the presence of hypoalbuminemia was not a risk factor affecting long-term outcome in patients with massive proteinuria." (PMID 35488221, 2022). "Other risk factors were duration of surgery > 120 min, administration of steroids, hypoalbuminemia, elevated creatinine, blood urea nitrogen, hematocrit, platelets, glucose, white blood cell count, abnormal neutrophil-to-lymphocyte ratio and elevated hsCRP-to-albumin ratio." (PMID 36225784, 2022). "Therefore, albumin administration is often used in cardiovascular disease patients with hypoalbuminemia and edema, however, it also increases the load of the heart and may cause congestive heart failure and other cardiac complications." (PMID 36337861, 2022). "While septic patients showed lower plasma albumin levels than non-septic patients, albumin synthesis was similar in the two groups suggesting that hypoalbuminemia during sepsis was not caused by suppressed hepatic production but a result of enhanced clearance from the circulation." (PMID 34920728, 2021). "Patients in the hypoalbuminemia group had significantly lower serum albumin level at admission than those in the normal group [2.5 (2.1–2.9) vs 3.3 (3.2–3.7), P < 0.01], along with the lowest in-hospital albumin level [2.2 (1.9–2.6) vs 3.3 (3.1–3.5), P < 0.01]." (PMID 34934165, 2021). "Therefore, it may be concluded that hypoalbuminaemia is a useful therapeutic target and that albumin supplementation would be an effective therapeutic strategy." (PMID 34043668, 2021). "A retrospective analysis of data from more than 20,000 emergency medical patients in Ireland found that hypoalbuminemia is independently associated with 30-day in-hospital mortality, with a non-linear relationship between mortality and on-admission albumin levels." (PMID 34921151, 2021). "In 1987, Inoue and his colleagues had first proposed that hypoalbuminemia influences the potency of furosemide and that the co-administration of albumin and furosemide could increase the diuretic response in comparison to furosemide alone in both animal and human models." (PMID 34851962, 2021). "Hypoalbuminemia is a feature of acute and chronic inflammation, as depicted by the inverse association with hs-CRP, and might favor thrombosis at the site of vascular lesion as albumin encompasses anticoagulant and antiplatelet properties." (PMID 34218413, 2021). "Concentrations of endogenous antioxidants including albumin, bilirubin, and uric acid were lower in the patients compared with the controls (albumin; bilirubin: p<0.001; uric acid: p<0.01); however, none of the patients with AN presented hypouricaemia, hypobilirubinaemia or hypoalbuminemia." (PMID 33883041, 2021). "The important role of serum albumin in the development of heart failure was underscored in a multicenter study of community-dwelling adults without heart failure: baseline hypoalbuminemia was associated with increased risk of incident heart failure during the 10-year follow-up." (PMID 33805128, 2021). "While septic patients showed lower plasma albumin levels than non-septic patients, albumin synthesis was similar in the two groups suggesting that hypoalbuminemia was not caused by suppressed hepatic production but a consequence of enhanced clearance from the circulation." (PMID 34920728, 2021). "Given that the inflection point (41.4 g/L) is just around the lower limit of the normal range for albumin (40–55 g/L), these results indicate that patients with clinical hypoalbuminemia may have slightly higher HbA1c levels than those with normal albumin levels." (PMID 34055818, 2021). "This hypothesis will imply that a minimal albumin loss, without any clinical symptoms of hypoalbuminaemia, might be beneficial, allowing a decrease in PBTU levels that have been difficult to eliminate with extracorporeal strategies until now." (PMID 34073439, 2021).